CRP (C-reactive protein)
Diseases named in the same sentence as CRP in open-access papers (continued):
Sharing a sentence is not in itself a finding about the gene and the disease.
diabetes (continued). "In the bivariate analysis, both 30- and 60-days mortality were significantly associated with older age, hypertension, heart disease, diabetes, low albumin levels and high CRP to albumin ratio (CAR)." (PMID 34940406, 2021). "Age, sex, chronic obstructive pulmonary disease, diabetes, heart failure, coronary heart disease, intensive care unit treatment, in-hospital thrombotic events, D-dimer, C-reactive protein, troponin, and albumin levels were associated with mortality." (PMID 34218413, 2021). "Those with elevated CRP (>3 mg/L) were likely to have higher BMI, to have diabetes and to have elevated 10-year predicted CVD risk and to have a lower estimated CD4 T-cell count." (PMID 34117263, 2021). "The age, BMI, past smoker, diabetes, hypertension, and C-reactive protein were negatively associated with relative telomere length." (PMID 34603596, 2021). "Uex1MH was inversely associated with past smoking behavior, medical history of diabetes mellitus, antidiabetic medication use, and CRP concentrations." (PMID 34091671, 2021). "The common risk factors for both diseases include: smoking, diabetes, male gender, age, obesity, dyslipidemia and increased CRP and fibrinogen levels." (PMID 33407375, 2021). "We therefore aimed to assess the associations of these four inflammatory markers, i.e. CRP, calprotectin, neopterin and lactoferrin, with the risk of cardiovascular mortality and if the associations differ according to diabetes status." (PMID 34341370, 2021). "The results revealed that the low IL-37, diabetes mellitus, high CRP, NT-pro BNP, and hs-cTnI were independent risk markers for poor prognosis." (PMID 34580597, 2021). "The positive association of salivary CRP and HbA1C suggests that inflammation is the main hallmark of insulin resistance which is observed in type 2 diabetes mellitus." (PMID 33676486, 2021). "In the StrongHeart study, elevated CRP levels also predicted HF risk in individuals with diabetes or metabolic syndrome." (PMID 34583686, 2021). "It was also found that high sensitivity CRP was directly proportional to the cholesterol and low-density lipoprotein levels which were the risk factor of pre-diabetes, taken as a secondary outcome." (PMID 34868746, 2021). "Recent studies found an association between increased CRP levels in patients with periodontitis and other systemic conditions such as coronary heart disease, stroke, or diabetes mellitus." (PMID 33796948, 2021). "We found that in addition to the traditional risk factors such as overweight, smoking, hypertension, diabetes, and hypercholesterolemia, CRP was also an independent risk factor for ACS in young women." (PMID 34900087, 2021). "Multiple regression analysis showed that the duration of diabetes, hs-CRP level, FPG, and BMI were independent risk factors for elevated baPWV, while the HDL-C level was an independent protective factor for baPWV." (PMID 33628837, 2021). "Insulin resistance (IR) and diabetes have also been associated with the activation of inflammatory mediators like C-reactive protein (CRP), IL-1β, TNF-α and IL-6 in blood and adipose tissue." (PMID 34026558, 2021). "Elevated CRP has been associated with an increased risk of diabetes in middle-aged and elderly Chinese." (PMID 34527591, 2021). "This is consistent with the findings from our study that showed that the duration of diabetes morbidity, HbA1c, CRP, and systolic blood pressure was a risk factor for DR in patients with type 2 diabetes." (PMID 33790859, 2021). "CRP levels have also been shown to predict the CVD outcomes/prognosis/risk factors in asymptomatic incident diabetes patients." (PMID 34367842, 2021). "Modest elevation of CRP can occur chronically, regarded as low-grade systemic inflammation, which has been associated with increased risks of cardiovascular disease, diabetes, or other adverse health outcomes, all conditions characterized by abdominal fat." (PMID 32827080, 2021).
diabetes (continued). "High salivary CRP levels indicate a low grade inflammatory process that accompanies types 2 diabetes mellitus and has exhibited a highly significant diagnostic capability." (PMID 33676486, 2021). "Recent studies have shown that diabetes, obesity and elevated levels of CRP, TNF-alpha and leptin are closely associated." (PMID 34923973, 2021). "Other studies reported a high-CRP association only with diabetes-induced complications, like nephropathy and cardiovascular risk." (PMID 34314447, 2021). "They showed that metabolically unhealthy obese participants (defined by high blood pressure, HDL, diabetes, waist circumference, and C-reactive protein) were at higher risk of all-cause mortality compared with their metabolically healthy obese counterparts." (PMID 33917005, 2021). "In participants with diabetes, higher CRP concentration was associated with PAD (1.19; 1.03 to 1.41, p=0.046) but not nephropathy (1.13; 0.97 to 1.31, p=0.120)." (PMID 32665312, 2020). "Baseline CRP has previously been shown to associate strongly with the incidence of diabetes mellitus in the MDC-CC." (PMID 33066363, 2020). "In this study, higher CRP concentration was associated with higher odds of diabetes in sub-Saharan Africans." (PMID 32665312, 2020). "Prospective epidemiologic studies demonstrated that obesity, smoking, high blood pressure and diabetes are independently associated with elevated levels of CRP and other inflammatory biomarkers." (PMID 32993521, 2020). "Third, the sample size among individuals with diabetes was relatively small, limiting the power to detect associations between CRP and vascular complications in diabetes." (PMID 32665312, 2020). "Previously, we have shown that diabetes is associated with increased valvular inflammation, measured by valvular CRP expression." (PMID 32552684, 2020). "A novel risk score for the prediction of AL using Sex, diabetes history, anastomotic type, reconstruction route, smoking history, CRP level and the presence of cardiac arrhythmia was developed and internally validated." (PMID 32252738, 2020). "It has been well documented that the appearance of peripheral neuropathy in type 1 and type 2 diabetes mellitus is strongly associated with increases in inflammatory biomarkers, including C-reactive protein, TNF-α, and IL-6." (PMID 32973438, 2020). "Herein, the numbers of CD45+ and CD3+ inflammatory cells were quantified and correlated with the AF risk factors age, gender, diabetes, and blood CRP levels." (PMID 32072262, 2020). "In the fully adjusted models, higher CRP concentration was significantly associated with diabetes (adjusted OR 1.13; 95% CI 1.05 to 1.21, p=0.002)." (PMID 32665312, 2020). "Diabetes mellitus, dyslipidemia, waist-to-hip ratio and metabolic syndrome were associated with higher hs-CRP levels." (PMID 33299770, 2020). "Age and sex, proteinuria, blood pressure, diabetes, cardiovascular disease and medications (antihypertensive drugs and statins), and C-reactive protein partly explained the lower risk of mortality observed for East Asians." (PMID 32517714, 2020). "As secondary analyses, we also examined the association between baseline (2013), and cumulative average of high sensitivity CRP (hs-CRP) and future diabetes risk." (PMID 32612667, 2020). "The Best-fit Risk Score included UACR (4 points), SBP (29 points), CRP (2 points), triglyceride (5 points), sex (13 points), education (− 10 points), and diabetes (18 points)." (PMID 32252667, 2020). "Among participants with diabetes, higher CRP Z-score concentration was also associated with PAD and nephropathy." (PMID 32665312, 2020). "High circulating acute phase inflammatory markers, i.e., C-reactive protein and fibrinogen have been linked to chronic inflammatory diseases such as MetS, diabetes, obesity, and CVD." (PMID 32164233, 2020).
diabetes (continued). "Among the 75 patients with cavitary MAC-PD, univariate analysis identified age, low BMI, high C-reactive protein, diabetes mellitus, concurrent CPA, and acquired CAM resistance as risk factors for death." (PMID 32370226, 2020). "AHR transcript (relative to that of GAPDH) turned out to be an independent risk factor of increased CRP levels [β Coefficient: 9.25(0.46–18.03), P = 0.040*], even after adjusting sex, age, disease status (diabetes duration and medications)." (PMID 32849564, 2020). "Indices of cytokine profile and C-reactive protein in patients with COPD with concomitant type 2 diabetes mellitus depending on the MDR1 (C3435T) gene polymorphism." (PMID 33072207, 2020). "Although studies have shown a positive relationship between CRP and diabetes, this association is often reduced or attenuated completely when anthropometric body measures, such as body mass index and hip-waist ratio, are accounted for in the analyses." (PMID 32879892, 2020). "From our literature search, we identified age, ASA class, BMI, preoperative length of stay and diabetes as general risk factors, while CRP, temperature and antibiotic use were identified as general risk factors because of this study." (PMID 33112893, 2020). "Among participants with diabetes, higher CRP Z-score concentration was associated with higher odds of albuminuria, but not with low eGFR in the unadjusted model." (PMID 32665312, 2020). "Higher CRP Z-score concentration was associated with higher odds of diabetes in the unadjusted model." (PMID 32665312, 2020). "We performed a cohort study to evaluate the association between the CRP trajectory and incident diabetes in Chinese adults." (PMID 32612667, 2020). "In the analysis of the association between higher CRP Z-score concentration and the individual components of nephropathy, higher CRP Z-score concentration was associated with higher odds of albuminuria and low eGFR in the non-diabetes group." (PMID 32665312, 2020). "Both baseline and the cumulative average hs-CRP were associated with high risk of incident diabetes." (PMID 32612667, 2020). "It should be emphasized that almost all studies analyzing the association between periodontitis and serum CRP levels have evaluated individuals with any systemic changes, such as cardiovascular disease, diabetes or rheumatoid arthritis." (PMID 32994872, 2020). "We subsequently correlated the clinical risk factor diabetes, gender, age, and CRP blood levels with the inflammatory cell density in the atria." (PMID 32072262, 2020). "The results of their study showed that CRP, white blood cell count and platelet-lymphocyte ratio mediated 8%, 13% and 16% of the association between severe periodontitis and diabetes." (PMID 32994872, 2020). "The results of our study in Ghanaians suggest an association between higher CRP and higher odds of diabetes in sub-Saharan Africans." (PMID 32665312, 2020). "Among all the other risk factors (cardiovascular history, age, duration of dialysis, haemoglobin, CRP), only the presence of diabetes increased the risk of overall (OR 2.73) and cardiovascular (OR 2.88) mortality." (PMID 32792012, 2020). "AHR transcript (relative to that of GAPDH) turned out to be the only independent risk factor of increased CRP levels [β Coefficient: 55.04(18.65–91.43), P = 0.005**], even after adjusting sex, age, disease status (diabetes duration, and medications)." (PMID 32849564, 2020). "In the secondary analyses, two single-measured hs-CRP concentration (in 2013 or in 2015) and the average of hs-CRP were associated with high risk of diabetes (P-trend< 0.01 for all)." (PMID 32612667, 2020). "Fourth, clinical data regarding estimated glomerular filtration rate, diabetes, hypertension, heart failure, underlying chronic kidney disease, C-reactive protein, mean arterial pressure, and hemoglobin for these patients were not collected in this study." (PMID 32610429, 2020).
diabetes (continued). "Using a sample of Ghanaians, we showed that among sub-Saharan Africans higher CRP concentration is associated with higher odds of diabetes, even after adjustments for the conventional cardiovascular risk factors." (PMID 32665312, 2020). "IL-6 promotes the production by T cells and macrophages of CRP associated with increased risk of diabetes, hypertension, and cardiovascular disease." (PMID 32023901, 2020). "Factors, such as smoking, obesity, diabetes and pregnancy have been associated with high serum levels of CRP." (PMID 32994872, 2020). "The primary health endpoints of indicators of CVD (blood pressure and CRP) and diabetes risk (HbA1c) were selected in response to the substantial global burden of premature mortality and morbidity from cardiometabolic diseases." (PMID 31286921, 2019). "Traditional risk factors of CKD including diabetes, blood pressure, C-reactive protein and baseline renal function were considered in adjustments and sensitivity analyses." (PMID 30791918, 2019). "But diabetes mellitus showed a statistical association with leukocytosis as well as elevated CRP levels." (PMID 31088357, 2019). "Obesity was significantly associated with diabetes, social class, hypertension, CRP-level, triglyceride level, and inversely related to high density lipoprotein level." (PMID 31000730, 2019). "Low-grade elevation of inflammatory markers such as CRP in older adults has been associated with a number of chronic conditions, such as cardiovascular disease, diabetes, physical disability, and cognitive decline." (PMID 30728031, 2019). "In this study, which excluded patients with a lifetime history of medical disorders including atherosclerosis and diabetes, we confirmed that higher BMI was strongly associated with higher CRP levels." (PMID 29764522, 2019). "In the univariate analysis, five risk factors with P values < 0.1 (age, diabetes, operation time, CRP and AFR) were selected for multivariate analysis." (PMID 31533682, 2019). "The findings of this study highlight the importance of dietary phytate intake in reducing the risk of various chronic diseases that are related to CRP concentration such as CVDs and diabetes." (PMID 31052485, 2019). "CRP and high-sensitivity CRP values were associated with AS in patients with metabolic syndrome, renal transplant, diabetes mellitus, and rheumatoid arthritis." (PMID 30857217, 2019). "This study first proved the role and partial regulation mechanism of CRP in altering cell morphology during infection and provided a theoretical basis for elucidating the mechanism in diabetes mellitus susceptible to K. pneumoniae." (PMID 32038513, 2019). "In contrast, among women adjustment for adiponectin (−30%) and CRP (−13%) attenuated the associations of height with diabetes, in addition to lipid markers and HbA1c." (PMID 31501920, 2019). "Studies with adults have shown risk of type 2 diabetes mellitus (DM2) development to be highly associated with increased CRP, suggesting that low-grade chronic inflammation coexists with glucose intolerance and compensatory increase in insulin secretion." (PMID 31143476, 2019). "Several cofactors including age, hypertension, smoking history, diabetes, and increased C-reactive protein levels are associated with poor coronary blood flow." (PMID 31008104, 2019). "Older age, high C-reactive protein level, and diabetes mellitus are risk factors for higher mortality." (PMID 31563057, 2019). "Inflammatory markers such as C-reactive protein (CRP) have been associated with impaired pulmonary function among subjects with diabetes." (PMID 31304013, 2019). "The significant associations are in several major phenotype groups: C reactive protein, lipid profile, diabetes, cystatin C, heart event risk, heart rate, and height." (PMID 30704471, 2019). "Studies have linked inflammatory biomarkers to various diseases; resistin has been linked with diabetes, CRP with malaria and P-selectin with systemic inflammatory response syndrome." (PMID 31856765, 2019).
diabetes (continued). "Generally, BP, triacylglycerols, CRP and adiponectin appeared to be more strongly correlated with height among women and seemed to play a stronger role in the association of height with diabetes than among men." (PMID 31501920, 2019). "Adjustment for liver fat and triacylglycerols, adiponectin and C-reactive protein substantially attenuated associations between height and diabetes risk, particularly among women." (PMID 31501920, 2019). "In subgroup analysis, changes in serum concentrations of CRP were significantly associated with short diabetes duration (− 0.23 mg/L, 95% CI, − 0.41 to − 0.05)." (PMID 31208420, 2019). "IHD was significantly associated with social class and diabetes, and stroke was strongly associated with age, while hypertension was associated with age, social class, obesity and CRP-levels." (PMID 31000730, 2019). "Whereas, low intakes of whole grains, fruits, and vegetables in the highest DII quintile have been related with reduced diabetes risk, probably mediated by a reduction of CRP, and certain interleukins, and by an improvement in the endothelial function." (PMID 29561774, 2018). "The order of important variables in the ANN model containing six parameters was as follow: family history of diabetes, hs-CRP, TC, BPS, TG, and age risk factor diabetic." (PMID 29374085, 2018). "Several risk factors, such as elevated CRP level, low albumin level, older age, low BMI, and diabetes mellitus, have been reported to be associated with early mortality after PEG." (PMID 29954339, 2018). "Possible explanation is that exposure to particle matters is associated with reduced heart rate variability, increased C-reactive protein levels and elevated inflammatory markers, which shared the same pathway with diabetes." (PMID 30012150, 2018). "In comparison, our study included more samples (17,967 and 69,033 participants for measuring SNPs-CRP and SNPs-diabetes associations, respectively)." (PMID 30619477, 2018). "CRP is a substantial inflammatory marker associated to increased risk of coronary artery disease in subjects with diabetes mellitus (Pfützner and Forst, 2006)." (PMID 30233283, 2018). "The high association (OR 1.49; 95% CI 1.03–2.15, p = 0.03) between serum CRP and the risk of diabetes was observed in a Norfolk cohort including 293 diabetes cases and 708 controls." (PMID 30619477, 2018). "Risk factors for PAD include age, diabetes mellitus, smoking, renal disease, hyperlipidemia, hypertension and other non-traditional risk factors, i.e., ethnicity, metabolic disorders, and C-reactive protein (CRP)." (PMID 29315259, 2018). "sVCAM-1 levels were associated with Diabetes mellitus (P < 0.05) and hs-CRP levels were associated with Diabetes mellitus and hypertension (P < 0.05)." (PMID 30301260, 2018). "In contrast in the Singapore Malay Eye Study on patients with diabetes, higher CRP levels and higher body mass index were associated with a lower frequency of diabetic retinopathy in a multivariate analysis." (PMID 30281641, 2018). "The associations between SNPs and CRP were measured on 5,274 men and women, and the associations between SNPs and diabetes were observed among 1,923 patients and 2,932 controls." (PMID 30619477, 2018). "As another inflammatory marker, CRP has been shown to be associated with an increased risk for development of type 2 diabetes mellitus (T2DM)." (PMID 29706998, 2018). "Inflammatory cytokines, such as CRP, are associated with obesity and consequently, increased risk of insulin resistance, diabetes mellitus, hypertension and dyslipidemia." (PMID 30820209, 2018). "Other examples include studies examining the causal role of CRP, lipoprotein (a), and vitamin D levels with different cardiovascular outcomes, or the association of homocysteine levels with diabetes mellitus." (PMID 30203249, 2018).